REV3L (REV3 like, DNA directed polymerase zeta catalytic subunit)
Description:
Catalytic subunit of the DNA polymerase zeta complex, an error-prone polymerase specialized in translesion DNA synthesis (TLS). Lacks an intrinsic 3'-5' exonuclease activity and thus has no proofreading function.
Synonyms: POLZ; REV3
Tractability: Small molecule: a structure with a bound ligand is known; it belongs to a druggable protein family. PROTAC: ubiquitination databases record sites on it; its protein half-life has been measured.
Gene: Protein-coding gene on chromosome 6 (111,299,028 to 111,483,715, reverse strand). Ensembl gene ENSG00000009413.
Subcellular location: Nucleus
Subcellular location (Human Protein Atlas): Nucleoplasm
Pathways (Reactome):
DNA Repair: Translesion synthesis by POLI; Translesion synthesis by POLK; Translesion synthesis by REV1
Gene Ontology:
Molecular function: DNA polymerase activity; DNA-directed DNA polymerase activity; protein binding; DNA binding; nucleic acid binding; nucleotide binding
Biological process: DNA biosynthetic process; error-prone translesion synthesis; translesion synthesis; DNA-templated DNA replication; double-strand break repair via homologous recombination; DNA damage response; DNA repair
Cellular component: site of DNA damage; zeta DNA polymerase complex; nucleoplasm; nucleus; chromosome; nuclear lumen; nucleolus
Genetic constraint (gnomAD): Loss-of-function variants: 50 observed, 242.43 expected, observed/expected ratio (o/e) 0.21, 90% interval 0.16 to 0.26. The upper end of that interval is the gene's LOEUF score, 0.26, which puts it in group 1 of 6, group 1 being the genes least tolerant of losing a copy. Missense variants: 2,780 observed, 3,420.6 expected, observed/expected ratio (o/e) 0.81, 90% interval 0.79 to 0.84. Synonymous variants: 1,132 observed, 1,188.9 expected, observed/expected ratio (o/e) 0.95, 90% interval 0.91 to 1.
Homologues: Orthologues: chimpanzee REV3L (99% identical), macaque REV3L (98% identical), dog REV3L (93% identical), pig REV3L (92% identical), rabbit REV3L (92% identical), mouse Rev3l (87% identical), rat Rev3l (85% identical), guinea pig REV3L (81% identical), tropical clawed frog rev3l (58% identical), zebrafish rev3l (47% identical). Paralogues in human: POLD1 (10% identical), POLA1 (10% identical), NEXMIF (9% identical).
Diseases named in the same sentence as REV3L in open-access papers:
REV3L is named in the same sentence as 54 diseases in open-access papers, as found by Europe PMC text mining. Sharing a sentence is not in itself a finding about the gene and the disease. The quoted sentences say what the papers report.
lung carcinoma (9 papers, 2015 to 2023). "Previously, polymorphisms in a microRNA target site of REV3L were shown to be associated with lung cancer susceptibility." (PMID 30617275, 2020). "In conclusion, our study suggested that REV3L rs462779 was significantly associated with overall survival and lymph node metastasis in lung cancer patients with platinum-based chemotherapy, and HMGB1 rs1045411 was related to overall survival and T stage." (PMID 32489453, 2020). "Several reports have described consistent mutations in the REV3L gene in different cancer types, including, lung cancer, breast cancer, osteosarcoma, and head and neck cancer, and these mutations have been shown to confer tumorigenic properties." (PMID 29435169, 2018). "REV3L polymorphisms were also reported to be significantly associated with risk of lung cancer and breast cancer." (PMID 25781640, 2015). "The rs462779 in REV3L was significantly correlated with overall survival of lung cancer patients in the additive (P for log-rank=0.018) and recessive (P for log-rank=0.005) models." (PMID 32489453, 2020). "In this study, we investigate the associations of HMGB1 (rs1045411, rs1412125, and rs2249825), REV3L (rs462779 and rs465646) and NFE2L2 (rs6706649, rs6721961, and rs35652124) with platinum-based chemotherapy prognosis in lung cancer patients." (PMID 32489453, 2020). "Genotypes of REV3L rs462779 and HMGB1 rs1045411 may be biomarkers for predicting platinum-based chemotherapy prognosis in lung cancer patients." (PMID 32489453, 2020). "The REV3L rs462779 and HMGB1 rs1045411 may serve as prognosis markers in lung cancer patients with platinum-based chemotherapy." (PMID 32489453, 2020). "Whereas other studies found that the REV3L expression was downregulated in colon carcinomas independent of tumor grade, gastric cancer, and lung cancer." (PMID 25781640, 2015).
cervical carcinoma (8 papers, 2016 to 2025). A carcinoma arising from either the exocervical squamous epithelium or the endocervical glandular epithelium. "Studies demonstrated that downregulated REV3L significantly increased the sensitivity of cancer cells (such as glioma, non-small cell lung cancer, cervical cancer) to cisplatin 35-37." (PMID 39744159, 2025). "Cervical cancer studies have shown that inhibition of REV3L expression and overexpression, respectively, enhances sensitivity and resistance of cervical cancer cells to cisplatin." (PMID 36968845, 2023). "In agreement, it was recently reported that Polζ expression is higher in cervical cancer than in normal tissue; in cervical cancer, the depletion of Rev3L increased cisplatin sensitivity, while Rev3L overexpression conferred cisplatin resistance by decreasing cisplatin-induced apoptosis." (PMID 30208165, 2018). "Also, the expression levels and/or roles of miR-142, miR-33b, RAD51B, REV3L, and CDH5 in cervical cancer lymph node metastasis need further clarification." (PMID 32457603, 2020). "To determine if the same was true for TLS genes other than the TLS polymerases (POLH, POLI, POLK, REV1, and REV3L), we segregated the cervical cancers in the TCGA database based on whether they did or did not have increased expression of at least one TLS gene." (PMID 36266721, 2022). "We showed that four miRNAs (miR-502, miR-145, miR-142, and miR-33b) are independent and common prognostic biomarkers for patients with cervical cancer, and seven proteins (CXCL12, IGF1, PTPRC CDH5, RAD51B, REV3L, and WDHD1) are key genes significantly related to lymph node metastasis." (PMID 32457603, 2020).
glioma (7 papers, 2015 to 2025). A benign or malignant brain and spinal cord tumor that arises from glial cells (astrocytes, oligodendrocytes, ependymal cells). "REV3L/POLZ overexpression confers cisplatin resistance in a glioma cell line, while depletion of this protein diminishes cisplatin resistance." (PMID 34645978, 2021). "POLZ/REV3L has been linked to carcinogenesis in breast, lung, gliomas, and gastric cancers, and modulates cisplatin sensitivity." (PMID 32838755, 2020). "In this sense, increased levels of cisplatin-induced cell death were achieved by depletion of REV3L expression in several cancer models, including glioma, lung, and cervical cells." (PMID 31189884, 2019). "The engineered overexpression of Rev3L in a glioma cell line attenuated cisplatin-induced apoptosis, while depletion of this protein increased cell sensitivity to this drug." (PMID 30208165, 2018). "In glioma cells, REV3L overexpression facilitates cisplatin chemoresistance." (PMID 40913328, 2025).
breast cancer (6 papers, 2015 to 2021). A primary or metastatic malignant neoplasm involving the breast. "Other genetic variants in REV3L have been found to be associated with both disease development risk and patients’ survival for different tumor types, such as breast cancer, stomach cancer, and CRC." (PMID 30591675, 2018). "Here it was demonstrated that REV3L downmodulation displays a synergic effect when combined with cisplatin also in breast cancer model." (PMID 31189884, 2019). "Reports on genetic mutations in REV3L are consistent in several cancer types, including lung and breast cancer, and mutations in its UTR region prevent microRNAs (miRNAs) from silencing REV3L in cancer." (PMID 29435169, 2018).
colon carcinoma (4 papers, 2015 to 2025). "Our findings suggest mutations in REV3L causes protein mislocalization to the cytoplasm, breaking its interaction and is believed to form new protein interactions in cytoplasm contributing to colon cancer progression." (PMID 29435169, 2018). "hsa-miR-340 (miR-340), a microRNA down-regulated in colon cancer, was used to bind to and downregulate REV3L, and found to control the proliferation and induce the apoptosis of colon cancer cells (HCT-116 and DLD-1) via the MAPK pathway." (PMID 29435169, 2018). "We also observed that the expression of miR-340, a microRNA targeting REV3L, was suppressed in colon cancer." (PMID 29435169, 2018). "Taken together, our results suggest miR-340 downregulated REV3L, inhibited colon cancer growth, and significantly inhibited tumor cell proliferation." (PMID 29435169, 2018). "HCT-116 and DLD-1 colon cancer cells were transfected with pCMV and/or pCMV-miR-340 plasmids, and REV3L+miR-340 plasmids." (PMID 29435169, 2018). "It addition, it shows that miR-340, which is down-regulated in colon cancer, targets and downregulates REV3L, and regulates cancer cells apoptosis and proliferation in vitro and in vivo." (PMID 29435169, 2018). "Accordingly, our results suggest REV3L mislocation plays an important role in development of colon cancer and that the downregulation of REV3L by miR-340 controls proliferation and induces apoptosis." (PMID 29435169, 2018). "Nude mice model was used to determine the effect of miR-340 mediated blocking of REV3L in colon cancer progression in vivo." (PMID 29435169, 2018). "Downregulation of REV3L with miR-340 showed to control the colon cancer cell proliferation and induced apoptosis as shown by the cell viability assay, TUNEL assay and colony formation assay." (PMID 29435169, 2018). "This study was undertaken to determine how changes in the location and interactions of REV3L regulate colon cancer progression." (PMID 29435169, 2018). "This study was performed to investigate the changes in the location and interactions of REV3L and the impact in regulating colon cancer progression." (PMID 29435169, 2018). "Immunostaining was used to evaluate the subcellular localizations of REV3L in normal and colon cancer cells." (PMID 29435169, 2018). "The study was performed to determine how changes in the location and interactions of REV3L regulate colon cancer progression." (PMID 29435169, 2018). "On the other hand, immunostaining of REV3L in colon cancer cell lines HCT-116 and DLD-1 revealed its mislocalization to cytoplasm." (PMID 29435169, 2018). "In conclusion, the results obtained demonstrate the location and interactions of REV3L are quite different in colon cancer." (PMID 29435169, 2018). "In the present study, we report for the first time mislocalization of the nuclear bound DNA mismatch repair protein REV3L to cytoplasm in colon cancer cells as evidence by immunostaining results." (PMID 29435169, 2018). "Here, we report for the first time, miR-340 mediated REV3L downregulation inhibits colon cancer cell proliferation and induces apoptosis via the MAPK pathway." (PMID 29435169, 2018). "Conversely, another study revealed that inhibition of REV3L reduced colony formation of lung, breast, mesolioma, and colon tumor cell lines." (PMID 25781640, 2015). "Notably, miR-340 has been proven to suppress proliferation and induce apoptosis of colon cancer cells by regulating an important oncogene, REV3L." (PMID 40806335, 2025). "However, co-treatment of REV3L+miR-340+5-FU reduced the cytotoxicity of 5-FU suggesting that REV3L confers drug resistance to colon cancer cells." (PMID 29435169, 2018). "The mislocalized REV3L might interact with new proteins partners in the cytoplasm which in turn may play role in regulating colon cancer progression." (PMID 29435169, 2018). "Furthermore, this down-regulation of REV3L also diminished colon cancer cell migration, and down-regulated MMP-2 and MMP-9." (PMID 29435169, 2018).
colon carcinoma (continued). "Furthermore, miR-340 overexpressing HCT-116 colon cancer cells formed smaller tumors than pCMV overexpressing HCT-116 cells in our nude mouse model, indicating REV3L downregulation by miR-340 inhibited colon cancer tumor growth and progression in our xenograft model." (PMID 29435169, 2018). "A proximity ligation assay (PLA) was used to investigate interactions between REV3L, REV1, and MAD2L2 in normal (CCD-18Co) and colon cancer cells." (PMID 29435169, 2018). "However, the number of interactions between REV3L and REV1, REV3L and MAD2L2, and REV1 and MAD2L2 were reduced to 44/cell, 27/cell, and 26/cell, respectively, in HCT-116 colon cancer cells and to 19.2/cell, 59/cell, the 51/cell in DLD-1 colon cancer cells." (PMID 29435169, 2018). "Furthermore, a decreased expression of REV3L has also been reported in tumor compared with the adjacent non-malignant tissue in colon cancer." (PMID 30591675, 2018).
lymphoma (4 papers, 2011 to 2021). A malignant (clonal) proliferation of B- lymphocytes or T- lymphocytes which involves the lymph nodes, bone marrow and/or extranodal sites. "Pure populations of control and Rev3l-deficient lymphoma cells were introduced into recipient mice until palpable tumors formed (∼2 weeks)." (PMID 31410467, 2019). "REV3L was found to be necessary for proliferation of mouse embryonic fibroblasts and could inhibit mice lymphomas formation." (PMID 25781640, 2015).
non-small cell lung carcinoma (4 papers, 2011 to 2025). A group of at least three distinct histological types of lung cancer, including non-small cell squamous cell carcinoma, adenocarcinoma, and large cell carcinoma. "Moreover, REV3L knockdown combined with ATRi was reported to enhance cisplatin cytotoxicity in sensitive and resistant non-small cell lung cancer cells." (PMID 34676045, 2021).
Möbius Syndrome (3 papers, 2015 to 2020). "REV3 is essential for mammalian development: missense mutations in the human REV3L gene can cause Mobius syndrome which is associated with developmental abnormalities, and Rev3 knockout mice are embryonic lethal." (PMID 32330130, 2020). "The analysis also provided a number of candidate genes possibly causing the developmental defects observed in PS patients, among others REV3L, a gene coding for an error-prone DNA polymerase previously associated with Möbius Syndrome with variable phenotypes including pectoralis muscle agenesis." (PMID 27884122, 2016). "Mutations in the REV3L gene have been recently associated with Möbius syndrome (MBS), a rare congenital cranial dysinnervation disorder characterized by facial palsy and variable other congenital anomalies, including pectoralis muscle hypoplasia." (PMID 27884122, 2016).
cutaneous squamous cell carcinoma (2 papers, 2020 to 2025). "Their study revealed that PICSAR lncRNA sponges miR-485-5p in cisplatin-resistant cutaneous squamous cell carcinoma cells, which leads to REV3L overexpression and resistance of the cancerous cells to cisplatin." (PMID 40804316, 2025).
endometrial cancer (2 papers, 2020 to 2021). Primary or metastatic malignant neoplasm involving the endometrium (mucous membrane that lines the endometrial cavity). "Thirty six percent of colorectal, stomach and endometrial cancers with POLE mutations carried additional mutations in POLQ (E/Q), POLZ/REV3L (E/Z) or both DNA polymerases (E/Z/Q)." (PMID 32838755, 2020).
Fanconi anemia (2 papers, 2017 to 2020). Fanconi anemia (FA) is a hereditary DNA repair disorder characterized by progressive pancytopenia with bone marrow failure, variable congenital malformations and predisposition to develop hematological or solid tumors. "Due to their involvement in DNA repair, several groups have studied or focused their genome-wide results on variants affecting genes involved in the Fanconi anemia pathway, such as BRCA2/FANCD1, BRIP1/FANCJ, FANCC, FANCE, and REV3L/POLZ." (PMID 32585810, 2020).
lymph node metastasis (2 papers, 2020). "Patients carrying REV3L rs462779 TC or TT genotypes had a lower hazard (OR=0.38, 95% CI=0.17-0.89, P=0.025) of lymph node metastasis in the dominant model when compared with patients carrying CC genotype." (PMID 32489453, 2020).
squamous cell carcinoma (2 papers, 2016 to 2017). A carcinoma arising from squamous epithelial cells. "Whole exome sequencing on cisplatin-resistant metastatic squamous cell carcinoma of head and neck tumors revealed that inactivation of REV3L may inform treatment options in patients of recurrent squamous cell carcinoma of head and neck tumors." (PMID 29156722, 2017).
Burkitt lymphoma (1 paper, 2016). A rare form of malignant mature B-cell non-Hodgkin lymphoma. "We also investigated two reported human REV3L knockout lines designated 332 and 504, derived from the Burkitt lymphoma cell line BL2." (PMID 26727495, 2016).
colorectal tumors (1 paper, 2021). "It has been reported that the two main functional subunits of pol ζ, REV3L and REV7, play important roles in the development of lung tumors, breast tumors, colorectal tumors, and cervical tumors." (PMID 34281455, 2021).
congenital blindness (1 paper, 2022). "The contiguous deletion containing EFHC2 gene results in congenital blindness, and REV3L was one of candidate genes who can impair the activity of abducens nerves that endow eyes the ability of looking to the side." (PMID 35456484, 2022).
diabetes (1 paper, 2017). "Among single genetic variants consistently associated with diabetes-related metabolites, two (rs174550 (FADS1), rs3204953 (REV3L)) were significantly associated with type 2 diabetes in large-scale meta-analysis for type 2 diabetes." (PMID 28729637, 2017).
endometriosis (1 paper, 2025). The growth of functional endometrial tissue in anatomic sites outside the uterine body. "Subsequently, by LASSO regression analysis, we constructed prediction models for 15 diagnostic genes in the endometriosis cohort and 6 diagnostic genes in the SLE cohort, respectively, and identified four co-diagnostic genes (PMP22, QSOX1, REV3L, SP110)." (PMID 39744159, 2025). "Subsequently, by the intersection analysis, we obtained four overlapping genes (PMP22, QSOX1, REV3L, SP110) as potential co-diagnostic genes for SLE and endometriosis." (PMID 39744159, 2025). "In our research, REV3L was significantly downregulated in endometriosis patients and SLE patients, and primarily involved in the PROTEASOME and FC_GAMMA R_MEDIATED_PHAGOCYTOSIS pathway." (PMID 39744159, 2025). "Four co-diagnostic genes (PMP22, QSOX1, REV3L, SP110) were identified for endometriosis and SLE." (PMID 39744159, 2025). "Collectively, PMP22, QSOX1, REV3L, SP110 may serve as potential diagnostic biomarkers for early diagnosis and targeted therapy of endometriosis and SLE." (PMID 39744159, 2025). "For REV3L, the PROTEASOME pathway (NES = -1.7556, NP = 0.0082) was enriched in SLE, and FC_GAMMA R_MEDIATED_PHAGOCYTOSIS pathway (NES = - 1.8216, NP = 0.0040) was enriched in endometriosis." (PMID 39744159, 2025). "REV3L was not statistically significant, but its expression trend was consistent with that observed in the endometriosis training cohort." (PMID 39744159, 2025).
malignant mesothelioma (1 paper, 2021). A malignant neoplasm of the pleura or peritoneum, arising from mesothelial cells. "Clinically, REV3L/POLZ and REV1 germ line mutations were found to be significantly associated with longer overall survival of malignant mesothelioma patients after platinum-based therapy." (PMID 34645978, 2021).